ITPRID1 (ITPR interacting domain containing 1)
Synonyms: CCDC129; FLJ38344
Tractability: No criterion of Open Targets' tractability assessment is met for any kind of drug.
Gene: Protein-coding gene on chromosome 7 (31,514,090 to 31,656,504, forward strand). Ensembl gene ENSG00000180347.
Subcellular location (Human Protein Atlas): Nucleoplasm
Gene Ontology:
Molecular function: signaling receptor binding
Genetic constraint (gnomAD): Loss-of-function variants: 85 observed, 79.11 expected, observed/expected ratio (o/e) 1.07, 90% interval 0.9 to 1.29. The upper end of that interval is the gene's LOEUF score, 1.29, which puts it in group 5 of 6, group 1 being the genes least tolerant of losing a copy. Missense variants: 1,259 observed, 1,203.7 expected, observed/expected ratio (o/e) 1.05, 90% interval 1 to 1.1. Synonymous variants: 489 observed, 441.97 expected, observed/expected ratio (o/e) 1.11, 90% interval 1.03 to 1.19.
Homologues: Orthologues: chimpanzee ITPRID1 (94% identical), macaque ITPRID1 (90% identical), dog ITPRID1 (65% identical), rabbit ITPRID1 (60% identical), mouse Itprid1 (58% identical), pig ITPRID1 (58% identical), rat Itprid1 (57% identical), tropical clawed frog itprid1 (27% identical), zebrafish itprid1 (18% identical). Paralogues in human: ITPRID2 (21% identical), TESPA1 (8% identical).
Diseases named in the same sentence as ITPRID1 in open-access papers:
ITPRID1 is named in the same sentence as 5 diseases in open-access papers, as found by Europe PMC text mining. Sharing a sentence is not in itself a finding about the gene and the disease. The quoted sentences say what the papers report.
cancer (2 papers, 2019 to 2025). A tumor composed of atypical neoplastic, often pleomorphic cells that invade other tissues. "For example, AKR1B15, COL17A1, CRABP1, and ITPRID1 were downregulated in BRCA, COAD, and PRAD but upregulated in LUAD, highlighting their cancer type-specific regulatory behavior." (PMID 41439026, 2025).
tumor (1 paper, 2023). "The genes expression levels in the model were detected by qRT-PCR, and the results showed that they were highly expressed in 20 pairs of tumor and normal tissues (UNCX, SLC6A3, AGAP2-AS1, LINC00968, PTX3 and SBSPON), while ITPRID1, DCST2, ETV3L, and ENSG00000261327 were down-regulated." (PMID 36647156, 2023).
ITPRID1 also shares sentences with these, for which no sentence is quoted: atherosclerosis (1 paper); Hypertension (1); psoriasis (1).